MRPS6 (mitochondrial ribosomal protein S6)
Synonyms: MRP-S6; S6mt; C21orf101; RPMS6; bS6m
Tractability: Small molecule: a structure with a bound ligand is known. PROTAC: ubiquitination databases record sites on it; its protein half-life has been measured.
Gene: Protein-coding gene on chromosome 21 (34,073,224 to 34,362,252, forward strand). Ensembl gene ENSG00000243927.
Subcellular location: Mitochondrion
Subcellular location (Human Protein Atlas): Mitochondria
Pathways (Reactome):
Metabolism of proteins: Mitochondrial ribosome-associated quality control; Mitochondrial translation elongation; Mitochondrial translation initiation; Mitochondrial translation termination
Gene Ontology:
Molecular function: protein binding; small ribosomal subunit rRNA binding; structural constituent of ribosome; rRNA binding
Biological process: mitochondrial translation; translation
Cellular component: mitochondrial small ribosomal subunit; mitochondrion; mitochondrial inner membrane; small ribosomal subunit; ribosome
Genetic constraint (gnomAD): Loss-of-function variants: 6 observed, 11.42 expected, observed/expected ratio (o/e) 0.53, 90% interval 0.29 to 1.04. The upper end of that interval is the gene's LOEUF score, 1.04, which puts it in group 4 of 6, group 1 being the genes least tolerant of losing a copy. Missense variants: 164 observed, 154.43 expected, observed/expected ratio (o/e) 1.06, 90% interval 0.93 to 1.21. Synonymous variants: 61 observed, 57.13 expected, observed/expected ratio (o/e) 1.07, 90% interval 0.87 to 1.32.
Homologues: Orthologues: chimpanzee MRPS6 (100% identical), macaque MRPS6 (92% identical), rat Mrps6 (87% identical), mouse Mrps6 (86% identical), pig MRPS6 (78% identical), guinea pig MRPS6 (73% identical), tropical clawed frog mrps6 (66% identical), zebrafish mrps6 (48% identical).
Diseases named in the same sentence as MRPS6 in open-access papers:
MRPS6 is named in the same sentence as 19 diseases in open-access papers, as found by Europe PMC text mining. Sharing a sentence is not in itself a finding about the gene and the disease. The quoted sentences say what the papers report.
atherosclerosis (4 papers, 2017 to 2024). A disease characterized by the build-up of fatty material and calcium deposition in the arterial wall resulting in partial or complete occlusion of the arterial lumen. "In genetically predicted levels, higher expression of ANXA5, CCDC71L, MED8, MRAS, MRPS6, NTAN1, and SLA5A3 was positively associated with atherosclerosis risk." (PMID 39766313, 2024). "By MR analysis, these DEGs (e.g., MRAS, MRPS6, and SLC5A3) were linked to causal effects with adverse outcomes in atherosclerosis and MI." (PMID 39766313, 2024). "Of these genes, A2ML1, AGGF1, CBS, ECE1, GABRB3, GALNT2, MRPS6/SLC5A3, and SPG7 had documented associations with hypertension, ischemic stroke and methionine metabolism, atherosclerosis, and early-onset MI." (PMID 34252155, 2021). "Notably, MRAS, MRPS6, and SLC5A3 were specifically associated with both atherosclerosis and MI risk." (PMID 39766313, 2024). "MR analysis identified the causal relationship between foamy cell fate A-related genes (MRAS, MRPS6, and SLC5A3) and the incidence of atherosclerosis and myocardial infarction." (PMID 39766313, 2024).
breast carcinoma (3 papers, 2022 to 2025). "The overexpression of MRPS6 and MRPS23 in breast cancer cells and tissues is associated with increased tumor cell proliferation." (PMID 40371222, 2025). "Existing studies primarily investigate the role of MRPS6 in tumorigenesis, particularly in breast cancer, where it has been shown to exert tumor-promoting effects." (PMID 38919620, 2024). "MRPS6 gene was detected to be highly expressed after breast cancer surgery." (PMID 38919620, 2024). "Similarly, the overexpression of the MRPS6 and MRPS23 genes affected tumorigenic cellular processes in breast cancer and their knockdown decreased proliferation, expression of select mesenchymal marker and increased expression of tumor suppressor genes." (PMID 36119536, 2022).
diabetes (2 papers, 2022 to 2023). "Previous GWASs have shown that MRPS6 is associated with a variety of human diseases including diabetes." (PMID 35299963, 2022). "In all, our studies identify MRPS6 and UPRmt as novel modulators of GSIS and apoptosis in β-cells, contributing to our understanding of the molecular and cellular mechanisms of IGT, prediabetes, and diabetes." (PMID 37758822, 2023).
prediabetes (2 papers, 2022 to 2023). "In summary, we identified two novel SNPs (rs13052524 and rs62212118) in MRPS6/SLC5A3 that were associated with 2hPG in Hainan prediabetes." (PMID 35299963, 2022). "We identified that rs13052524 in MRPS6 and rs62212118 in SLC5A3 were associated with 2hPG in Hainan prediabetes (p = 4.35 × 10-6, p = 4.05 × 10-6, respectively)." (PMID 35299963, 2022). "Our study showed that rs13052524 and rs62212118 loci in the MRPS6 gene were related to 2hPG level in the Hainan prediabetes, suggesting that these two loci might play a certain function in the regulation of 2hPG level." (PMID 35299963, 2022). "We found two susceptibility loci in MRPS6/SLC5A3 genes associated with 2hPG, six loci in LINC01648, MATN1, CRAT37, and SLCO3A1 genes associated with HbA1C, and five loci in TRPM3/TMEM2 and MLYCD/OSGIN1 correlated to BMI in Hainan prediabetes." (PMID 35299963, 2022).
insulinoma (1 paper, 2023). "Also consistent with the insulinoma β-cell study, mRPS6 siRNA significantly reduced GSIS of primary mouse β-cells by ELISA." (PMID 37758822, 2023). "In this study, we show that MRPS6 but not SLC5A3 regulates glucose-stimulated insulin secretion (GSIS) in primary human β-cell and a mouse pancreatic insulinoma β-cell line." (PMID 37758822, 2023).
Parkinson disease (1 paper, 2021). A progressive degenerative disorder of the central nervous system characterized by loss of dopamine producing neurons in the substantia nigra and the presence of Lewy bodies in the substantia nigra and locus coeruleus. "bS6m (MRPS6)—MRPS6 was one of 11 differentially expressed transcripts identified in a gene array on post-mortem brain samples from patients with Parkinson’s disease." (PMID 33917098, 2021).
periodontitis (1 paper, 2025). An acute or chronic inflammatory process that affects the tissues that surround and support the teeth. "Previous studies have reported heterogeneity in gingival fibroblasts in periodontal tissues, with four subsets significantly altered in periodontitis: Fib 1.1 (CXCL1, CXCL2, CXCL13); Fib 1.2 (APCDD1, IGFBP2, MRPS6); Fib 1.3 (APOD, GSN, CFD); and Fib 1.4 (TIMP3, ASPN, COL11A1)." (PMID 40801798, 2025).
viral infection (1 paper, 2024). "In this seminal investigation, we provide the inaugural evidence substantiating the inhibitory impact of MRPS6 overexpression in HIEC-6 cells on PDCoV viral infection." (PMID 38919620, 2024).
infection (2 papers, 2024 to 2025). The state of being infected such as from the introduction of a foreign agent such as serum, vaccine, antigenic substance or organism. "In this investigation, we hypothesized that MRPS6 possesses the ability to impede the infection caused by PDCoV by exerting regulatory effects on the interferon type I (IFN-I) signaling pathway." (PMID 38919620, 2024). "Consequently, we further investigated the differential protein MRPS6, which exhibited the highest level of differential expression at 48 hours post-infection, for subsequent studies." (PMID 38919620, 2024).
tumor (2 papers, 2024). "Research on MRPS6 and GPT2 has mostly examined their role in increasing tumor cell proliferation and metastasis, with little attention paid to their role in AD." (PMID 38774875, 2024).
mitochondrial disease (1 paper, 2022). "Mitochondrial disease-causing mutations were found in thirteen small ribosomal subunit mitoribosomal proteins (MRPS1, MRPS2, MRPS6, MRPS7, MRPS9, MRPS11, MRPS14, MRPS16; MRPS22, MRPS23, MRPS25, MRPS34, MRPS39) and four large ribosomal mitochondrial proteins (MRPL3, MRPL12, MRPL24, MRPL44)." (PMID 36140315, 2022).
MRPS6 also shares sentences with these, for which no sentence is quoted: Anxiety (1 paper); copy number variation (1); coronary artery disease (1); endometriosis (1); Hyperglycemia (1); Hypertension (1); ischemic stroke (1); myocardial infarction (1).